TERT (telomerase reverse transcriptase)
Diseases named in the same sentence as TERT in open-access papers (continued):
Sharing a sentence is not in itself a finding about the gene and the disease.
tumor (continued). "The Wilms tumor gene (WT1) is deleted or mutated to an inactive form in a fraction of Wilms tumors and is a known repressor of TERT expression." (PMID 31757062, 2019). "Telomerase reverse transcriptase (TERT) is an essential enzyme for regulating cell immortalization as well as long-term tumor growth." (PMID 30791431, 2019). "The change in TERT expression during the different steps of skin carcinogenesis was analysed in keratoacanthomas (KA), as a paradigm for early tumour and in cSCCs, as the representative of invasively growing late-stage tumour." (PMID 30884806, 2019). "High tumor TERT levels also correlate with a worse response to treatment, and it has been demonstrated that TERT confers resistance to different apoptotic stimuli including treatment with chemotherapeutic agents and radiation." (PMID 31772219, 2019). "Half of the tumours in both groups showed TERT staining in 30–70% of the nuclei and the remaining cases a weak TERT staining." (PMID 30884806, 2019). "Because of multiple extra-telomeric functions of TERT, by TERT-bypassing mechanisms of tumor development and because of subtle epigenetic regulatory mechanisms of TERT activity." (PMID 31750255, 2019). "PTEN and VEGF are independent of other major prognostic factors including clinical features like age, tumor stage, and gender, molecular aberrations like TERT, and morphological factors like TCs." (PMID 31242620, 2019). "From relapsed tumor procured at autopsy, we established a cell line retaining the BRAF V600E mutation, TERT promoter mutation and CDKN2A/2B loss." (PMID 31345255, 2019). "Univariate analysis showed that risk score, age, TERT mutation status, TERT expression level, T stage, N stage, M stage, AJCC stage, and the largest dimension of the neoplasm were significantly associated with the PFI (p < 0.05)." (PMID 31803141, 2019). "The authors demonstrated that the butylidenephthalide wafers reduced the size of the tumors in a dose-dependent manner without relevant adverse effects in the animals, and induced a reduction in TERT mRNA expression which leads to tumor senescence." (PMID 31482066, 2019). "TERT levels in tumor cells were significantly higher in females (P = 0.023) and in patients with advanced stage disease (P < 0.001) and neck metastases (P < 0.001)." (PMID 31772219, 2019). "Immune tumor microenvironment, epithelial-mesenchymal transition, and some peculiar features including BRAFV600E mutation, TERT promoter mutations, and transcriptomic signatures have been described as predictors of aggressive DTC." (PMID 31617002, 2019). "Mutations in the TERT promoter have been detected in 3–7% of pediatric GBM and tumor cells in this group maintain or increase telomere length through alternative lengthening of telomeres (ALT) pathway." (PMID 30625996, 2019). "Running TERT in a multivariate analysis with PTEN including tumor stage, age and gender as covariables, TERT (p = 0.002; Exp(B) 3.737) and PTEN (p = 0.036; Exp(B) 0.259) were independent parameters." (PMID 31242620, 2019). "Our analysis illuminated a tumor evolutionary series of events, which included 1p/19q codeletion, IDH1 R132H, and TERT C250T as early events, followed by loss of function of NDST4 and mutations in FUBP1 and CIC as late events." (PMID 31217899, 2019).
tumor (continued). "The prominent role of telomerase in human cancers has encouraged the development of telomerase inhibitors to suppress tumour growth and gene therapy and immunotherapy have been proposed to potentially control TERT expression in tumours." (PMID 30884806, 2019). "The analysis by capillary sequencing of the TERT gene promoter region was successful in 72 out of 93 tumor samples." (PMID 29464027, 2018). "Tumor DNA was isolated fromformalin-fixed paraffin-embedded (FFPE) tumor tissue, as previously reported.TERT promoter mutations were identified by PCR followed bydirect sequencing (Vinagreet al., 2013; Batistaet al., 2016)." (PMID 29473934, 2018). "It is becoming sequentially more understandable that based on the positive and negative regulation of TERT, miRNAs are categorized into oncogenic and tumor suppressor miRNAs." (PMID 29614790, 2018). "TERT promoter mutations appear to be rare in PTC (4.4%, n = 455, Chinese population), but they correlate positively with aggressiveness of the tumor and patient age." (PMID 30089490, 2018). "HBV integration into growth control genes (such as TERT), pro-oncogenic genes, or tumor suppressor genes and the oncogenic activity of truncated HBx promote hepatocarcinogenesis." (PMID 30073017, 2018). "Future studies must converge on the identification of natural products and synthetic compounds which can inhibit TERT via stimulating the expression of tumor suppressor miRNAs." (PMID 29614790, 2018). "Even expression of a TERT mutant that retained the catalytic activity but was incapable of maintaining telomere length promoted tumor formation in nude mice." (PMID 29422527, 2018). "These genes encode telomerase reverse transcriptase (TERT), vascular endothelial growth factor A (VGFA), MET, and MYC proteins that are known to have a role in tumor growth." (PMID 30228976, 2018). "Telomerase inhibitors remain an attractive approach to target cancer cells, given the specificity of TERT expression in tumor cells." (PMID 29643934, 2018). "Interestingly, the occurrence of TERT promoter mutations in 37.5% of CIN1 observed in our results suggests that the UV-induced DNA damage may precede the progression of conjunctiva early lesions to high grade neoplasia." (PMID 29562930, 2018). "In our study CC>TT substitutions in TERT promoter were very frequent in accordance with their overall frequency in other UV-related tumours." (PMID 29562930, 2018). "The adenomyoepithelioma component likely displayed intra-tumor genetic heterogeneity, given that it harbored a subclonal EPHB1 missense mutation and a subclonal TERT promoter hotspot mutation." (PMID 29739933, 2018). "Age and MGMT promoter methylation were identified as independent prognostic biomarkers, and the TERT promoter mutation status and MGMT promoter methylation status, when combined with other tumor‐related factors, generated several different survival subgroups." (PMID 29984907, 2018). "Some studies have found that Par-4 can interact with TERT in the cytoplasm, preventing Par-4 from translocating to the nucleus in tumour cells." (PMID 30186877, 2018). "This wide data collection enabled us to portray, by organ/system and histotypes, the prevalence of TERTp mutations, TERT and TERC amplifications, and ALT in human tumours." (PMID 29751586, 2018). "MYC and TERT genes were also affected by focal gains in 8q and 5p observed in 55% and 40% of the tumours respectively." (PMID 29416628, 2018). "High-risk and high-stage neuroblastoma (NBL) (15%) is, so far, the best characterized tumour model for rearrangements of the TERT gene (cohort of 292 patients)." (PMID 29751586, 2018).
tumor (continued). "No data is available with regard to the possibility of increased expression of C/EBP—due to FUS-DDIT3—increasing TERT expression in tumor cells." (PMID 29463038, 2018). "Scientists have started to identify the miRNAs which cell-type-specifically control TERT but we still have insufficient understanding about the mechanisms used by TERT to transcriptionally inhibit tumor suppressors and stimulate oncogenic miRNAs." (PMID 29614790, 2018). "Telomerase reverse transcriptase (TERT) had the highest number of hypermethylated sites and was found to be associated with tumor progression and poor prognosis in NB." (PMID 29774131, 2018). "Diagnostically useful is the additional testing for mutations in the promoter region of telomerase reverse transcriptase (TERT), which leads to an upregulation of the telomerase complex activity, increasing tumour cell survival." (PMID 29098416, 2018). "Most TERT inhibitors evaluated thus far target the enzymatic activity of telomerase and rely on critical shortening of telomeres to kill tumor cells; consequently, there is a prolonged lag period for efficacy." (PMID 29695835, 2018). "TERT, the catalytic subunit of telomerase, is a promising therapeutic target for cancer, as it is highly expressed in most tumor cells and seldom expressed in most normal cells." (PMID 29695835, 2018). "Elevated TERT functions as a strong oncoprotein, robustly promoting aggressive behaviors of cancer cells and tumor development." (PMID 29422527, 2018). "Either administration of PLX4032 or TERT knockdown inhibited tumor growth and combination of the two nearly completely abolished tumor growth, particularly evident in tumor weight." (PMID 29422527, 2018). "In this section, we draw attention to the recent progress made in outlining the mechanisms opted by TERT to repress expression of tumor suppressor miRNAs." (PMID 29614790, 2018). "In CCHCC, our data demonstrated that TERT cytoplasmic expression elevated in the malignant alteration, correlated with multiple numbers of tumors and tumor recurrence." (PMID 28460432, 2017). "TERT promoter mutations were frequent in the BRAF, RAS, and NF1 subtypes (ranging from 72% to 83%), while they are rare in Triple-WT (about 7%); in this last tumor subtype, alternative mechanisms (gene amplification) are involved in TERT activation." (PMID 29156643, 2017). "Our immunotherapeutic treatment based on anti-TERT CTLs infusion significantly controlled tumour growth inducing a survival benefit on treated mice compared to mice treated with hHCV1406-1415-specific TCR-engineered T-cells." (PMID 29152058, 2017). "The tBMSCs promote GSC proliferation more effectively than TERT-BMSCs and normal BMSCs suggesting specific interactions during tumor development." (PMID 29262650, 2017). "One possible candidate is the TERT protein, which is subunit of telomerase and is highly expressed in tumor cells." (PMID 29262650, 2017). "We questioned if this tumor suppressor role of TIP60 was dependent on repression of the TERT promoter and telomerase activity." (PMID 29045464, 2017). "In this study, anti-tumor therapeutics targeting TERT was employed as a unique therapy strategy due to the high prevalence of telomerase in most of the tumor cells." (PMID 28420995, 2017). "The gene expression level (49.99 ± 10.23% for U87, 43.28 ± 9.66% for U251) and protein expression level (51.58 ± 7.88% for U87, 50.69 ± 7.59% for U251) of TERT is observed to decrease substantially after transfecting the tumor cells for 48 h." (PMID 28420995, 2017). "The dysfunction of TERT will prevent the long-term survival of tumor cells and promote cell apoptosis and death." (PMID 28420995, 2017). "The mutations generate a consensus binding site for the E-twenty-six transcription factor, which upregulates TERT expression and thus induces the maintenance of telomere length and tumor proliferation." (PMID 28915660, 2017).
tumor (continued). "TERT RNA-transfected human DCs also stimulated TERT-specific CTLs that effectively lysed tumor cells." (PMID 28477011, 2017). "Hypermethylation of TERT and BCL2 was associated with tumour grading, and BCL2 was associated with tumour stage." (PMID 29038612, 2017). "Accordingly, we expected that qRT-PCR detection of the tumor markers TERT and Survivin/BIRC5 would contribute to a sensitive assay of immortalized RPE cells." (PMID 28811571, 2017). "In CCHCC, both TERT cytoplasmic and nuclear expression levels in tumor tissues were significantly higher than that in corresponding adjacent tissues (P = 0.008 and P = 0.03, respectively, Mann-Whitney test)." (PMID 28460432, 2017). "TERT-WT and TERT-CI treated tumors displayed the largest volumes, while TERT-siRNA treated tumors showed smallest volumes than the control tumor group." (PMID 28765565, 2017). "The KrasG12D lung cancer mice model with TERT deletion showed telomere dysfunction increased lung epithelial apoptosis, delayed tumor formation and increased life span." (PMID 27329725, 2017). "TERT-siRNA treated tumor cells showed the slowest growth, displaying the smallest sizes after 4 weeks." (PMID 28765565, 2017). "We analyzed the TERT subcellular expression in paired adjacent and tumor tissues of NCCHCC and CCHCC by immunohistochemistry." (PMID 28460432, 2017). "Like other studies in which genetic factors were associated with late tumor recurrence in HCC24,25, TERT expression was significantly correlated with late IHR in this study." (PMID 28947783, 2017). "TERT conducts as a transcriptional modulator in tumor cells to sustain its own levels and to control the induction of target genes critical for tumor cell survival and proliferation." (PMID 29267201, 2017). "So, although the TERT/TERC/dyskerin complex in tumour cells is accepted as the leader form, pontin and reptin gene expressions must also be expected to increase." (PMID 28443573, 2017). "One carcinoma displayed subclonal acquisition of TERT promoter, ARID2, and PTEN mutations in 13% of tumor cells." (PMID 29101368, 2017). "The results demonstrated a high positive rate of TERT cytoplasmic localization (95%) in addition to nuclear localization (64%) in the tumor tissues of HCC." (PMID 28460432, 2017). "Data from both human and murine systems demonstrate that CTLs can recognize peptides derived from TERT and kill TERT-positive tumor cells." (PMID 28477011, 2017). "Compared to these methods, our team used anatomic location as basic tumor feature to predict biomarkers like IDH1/1p19q/TERT, which is more simple, cost effective and visualized." (PMID 28915860, 2017). "For example, some known oncogenes, such as KMT2B and TERT, were dominantly observed in tumor while fusion transcripts with CYP3A5, SERPING1, and WDR72 were only found in normal tissue." (PMID 29212479, 2017). "Whereas higher expression level of nuclear TERT was associated with early BCLC stage and smaller tumor size (P = 0.031 and P = 0.039, Mann-Whitney test)." (PMID 28460432, 2017). "Human telomerase reverse transcriptase (TERT) is the catalytic protein subunit of telomerase and it is very critical for the activity of telomerase in tumor cells." (PMID 28420995, 2017). "The IHC analysis of hCD20+ leukemic cells revealed a remarkable reduction in tumour accumulation in different tissues (spleen, BM, liver and kidney) in TERT-treated mice compared to control mice, therefore suggesting an effective control of leukemic spread." (PMID 29152058, 2017). "Molecular mechanisms of TERT upregulation are complex, tumor-specific and can be clinically relevant." (PMID 29100407, 2017). "Upregulation of the telomerase reverse transcriptase (TERT) gene in human cancers leads to telomerase activation, which contributes to the growth advantage and survival of tumor cells." (PMID 29100407, 2017).
tumor (continued). "Transformed tumour cells initially express TERT to acquire both an “immortalized” phenotype preventing cell apoptosis induced by the telomeres reduction and inducing self-renewal ability." (PMID 29152058, 2017). "In particular, we emphasized the ability of TERT-based ACT to promote a strong control of tumor growth in several cancer settings, while ignoring hematopoietic progenitors and activated T lymphocytes." (PMID 29152058, 2017). "Methylation at the TERT promoter has been observed in various tumor tissues and transformed cell lines." (PMID 26575952, 2016). "Upon infection, E1A and E1B are expressed and induce viral replication and cellular lysis in TERT promoter active tumor cells, while sparing TERT promoter inactive benign cells." (PMID 27240403, 2016). "The TERT expression level was significantly higher in HCC tumor with a methylated promoter than in that with an unmethylated promoter." (PMID 26575952, 2016). "Direct sequencing such as Sanger sequencing is regarded as a gold standard for the identification of mutant targets, however, its threshold sensitivity is at least 10% of mutant TERT promoter-containing tumor DNA." (PMID 27438857, 2016). "It has been reported that pTERTm is able to increase the transcriptional activity of TERT promoter in tumours and express higher level of TERT mRNA compared with wild type-tumours." (PMID 26799744, 2016). "All 758 tumor samples from Cohort 1 were screened for mutations in IDH1/2 and TERT hotspots and the copy number status of 1p/19q." (PMID 27503138, 2016). "In this regard, it is conceivable that the acquisition of pTERTm leading to TERT activation is an important event during cancer progression, as it allows tumour cells to avoid proliferation limitation and to acquire immortalization." (PMID 26799744, 2016). "In our study, TERT was increased in copy number in the human tumor samples, and the gene expression was also significantly up‐regulated." (PMID 26778414, 2016). "In cancer cells, TERT-derived peptides are processed and presented on tumor cells’ surface in the context of major histocompatibility complex (MHC) class I molecules." (PMID 27240403, 2016). "Costunolide-mediated decrease in tumor volume was accompanied by decreased expression of TERT, Nrf2, G6PD, TKT, and GS(P) levels." (PMID 27148686, 2016). "Suicide gene therapy: This strategy exploits the highly active TERT or TERC promoter in tumor cells to express cytotoxic products." (PMID 27240403, 2016). "BRAF and TERT promoter mutations were each significantly associated with high-risk clinicopathological features of PTC, such as old patient age, large tumor size, extrathyroidal invasion, capsular invasion, and advanced disease stages." (PMID 26943032, 2016). "In particular, mutations in the TERT promoter and FGFR3 are the most frequently detected, with rates comparable to those of other studies and reflecting the situation in primary tumor tissue." (PMID 27611947, 2016). "Originally described in melanoma, the mutations in human TERT promoter, mainly at -124 and -146 base pair positions from the ATG start site, have been shown to be common in certain tumor types including BC of all stages with mutation frequencies of up to 80%." (PMID 27611947, 2016). "The combination of 1p19q deletion and TERT and IDH1 mutational status separated tumor groups that showed distinct age of diagnosis and outcome." (PMID 27172220, 2016). "Expression of TERT, which is normally strongly repressed by multiple tumor suppressors and which plays a critical role in tumor formation and progression, is essential for unlimited cell growth and is under tight transcriptional control." (PMID 27501725, 2016).